NSUN7 (NOP2/Sun RNA methyltransferase family member 7)
Description:
Plays an essential for sperm flagellum assembly.
Synonyms: FLJ14001
Tractability: No criterion of Open Targets' tractability assessment is met for any kind of drug.
Gene: Protein-coding gene on chromosome 4 (40,749,776 to 40,811,184, forward strand). Ensembl gene ENSG00000179299.
Subcellular location: Cytoplasm; Cell projection, cilium, flagellum
Subcellular location (Human Protein Atlas): Vesicles
Gene Ontology:
Molecular function: methyltransferase activity
Biological process: flagellated sperm motility; sperm flagellum assembly
Cellular component: cytoplasm; sperm flagellum; motile cilium
Genetic constraint (gnomAD): Loss-of-function variants: 22 observed, 25.23 expected, observed/expected ratio (o/e) 0.87, 90% interval 0.62 to 1.25. The upper end of that interval is the gene's LOEUF score, 1.25, which puts it in group 5 of 6, group 1 being the genes least tolerant of losing a copy. Missense variants: 385 observed, 449.29 expected, observed/expected ratio (o/e) 0.86, 90% interval 0.79 to 0.93. Synonymous variants: 153 observed, 180.36 expected, observed/expected ratio (o/e) 0.85, 90% interval 0.74 to 0.97.
Homologues: Orthologues: chimpanzee NSUN7 (99% identical), macaque NSUN7 (96% identical), pig NSUN7 (82% identical), rabbit NSUN7 (82% identical), dog NSUN7 (79% identical), guinea pig NSUN7 (71% identical), rat Nsun7 (68% identical), mouse Nsun7 (66% identical), tropical clawed frog nsun7 (45% identical), Drosophila melanogaster CG44836 (18% identical).